TRIM31 (tripartite motif containing 31)
Diseases named in the same sentence as TRIM31 in open-access papers (continued):
Sharing a sentence is not in itself a finding about the gene and the disease.
Insulin resistance (2 papers, 2018 to 2022). Increased resistance towards insulin, that is, diminished effectiveness of insulin in reducing blood glucose levels. "The observed effects of Trim31 on Rhbdf2 signaling-associated hepatic steatosis, inflammation, and insulin resistance prompted us to examine whether Trim31 directly interacts with Rhbdf2 during the development of NAFLD." (PMID 35217669, 2022). "This may be the underlying mechanism by which the TRIM31−/− mice showed impaired glucose tolerance and insulin resistance." (PMID 29497383, 2018). "Given the tight correlation of Trim31 with fatty liver, we constructed a series of mice models to explore the role of Trim31 in the regulation of the major hallmarks of insulin resistance and glycometabolic disorder." (PMID 35217669, 2022). "The obtained results revealed that liver Trim31 is a crucial suppressor of HFD-triggered insulin resistance and abnormal glucose metabolism." (PMID 35217669, 2022). "Fasting serum insulin concentration and HOMA-IR were higher in TRIM31−/− mice, indicating insulin resistance in TRIM31−/− mice (P < 0.05)." (PMID 29497383, 2018). "Consistent with previous study, elevated p-IRS-1/IRS-1 protein expression, and decreased Akt Thr308 phosphorylation were observed in TRIM31−/− mice with impaired glucose tolerance and insulin resistance." (PMID 29497383, 2018). "TRIM31−/− mice showed glucose intolerance and insulin resistance, with a significant difference in gut microbiota composition, characterized by increased abundance of Prevotellaceae and Veillonellaceae." (PMID 29497383, 2018). "For the genetic factors, our study showed that TRIM31 knockout mice had glucose intolerance and insulin resistance." (PMID 29497383, 2018). "Therefore, Trim31-Rhbdf2 binding and the subsequent Rhbdf2 ubiquitination are required for and conduce to the mitigation of liver steatosis, insulin resistance, and liver inflammation triggered by hepatocyte Rhbdf2-MAP3K7 signaling." (PMID 35217669, 2022). "Furthermore, the hepatic Trim31 expression in mice is responsive to dietary interventions that significantly moderated insulin resistance, hepatic steatosis, and inflammation phenotype via mechanically, regulating Rhbdf2 proteasome degradation." (PMID 35217669, 2022). "In conclusion, and of functional relevance, we determined that liver Trim31 expression correlated with NAFLD/NASH and metabolic disorder e.g., insulin resistance and glycometabolic disorder both in humans and in murine." (PMID 35217669, 2022).
liver cancer (2 papers, 2022). An epithelial or non-epithelial malignant neoplasm that arises from the liver. "Overall, our results showed that the four specific genes, TIPIN, RBM15B, DUSP28, and TRIM31, were likely prognostic biomarkers of liver cancer, and TIPIN might conspicuously accelerate the process of hepatocarcinogenesis." (PMID 35082931, 2022).
nasopharyngeal carcinoma (2 papers, 2020 to 2022). A carcinoma arising from the nasopharyngeal epithelium. "Earlier, our group found that rare variants in TRIM31 have contributed to the genetic susceptibility of nasopharyngeal carcinoma (NPC), and higher TRIM31 expression is associated with poor overall survival (OS) of NPC." (PMID 35928444, 2022).
peritonitis (2 papers, 2016 to 2018). Inflammation of the peritoneum (tissue that lines the abdominal wall and covers most of the organs in the abdomen). "Consistent with that, TRIM31 deficiency facilitated NLRP3 inflammasome activation, enhanced IL-1β secretion and thus aggravated alum-induced peritonitis in vivo." (PMID 27929086, 2016). "In vivo experiments also confirmed the beneficial roles of TRIM31 in the alum-induced peritonitis, an NLRP3 dependent acute inflammatory model." (PMID 27929086, 2016). "More importantly, the previous study focused on an alum-induced peritonitis model, and found that TRIM31 could inhibit NLRP3 inflammasome activity in mouse peritonitis in vivo." (PMID 29497383, 2018). "We further investigated the effects of TRIM31 in an IL-1-dependent mouse peritonitis model." (PMID 27929086, 2016). "Consequently, TRIM31 deficiency enhances NLRP3 inflammasome activation and aggravates alum-induced peritonitis in vivo." (PMID 27929086, 2016).
steatosis (2 papers, 2022 to 2025). Increased lipid within the cytoplasm of cells. "In patients with NAFLD or NASH, we found that Trim31 levels were drastically reduced, but hepatic Rhbdf2 levels were increased, compared to the levels in non-steatosis samples." (PMID 35217669, 2022). "Of note, significantly lower expression levels of TRIM31 were observed in the livers from NASH patients than in those from patients with only simple steatosis." (PMID 35217669, 2022). "Similarly, in human subjects, the investigators found that TRIM31 tended to be reduced in the livers of patients with NASH compared to human livers without steatosis, and TRIM31 expression was negatively correlated with the severity of NASH." (PMID 40292292, 2025).
asthma (1 paper, 2022). "Nineteen differentially expressed PRGs were included in the mild-to-moderate and severe asthma samples, among which CAPN1, NLRP1, TRIM31, NOS2, and CDC37 showed the highest difference (P<0.01)." (PMID 35967302, 2022).
cardiomyopathy (1 paper, 2022). A disease of the heart muscle or myocardium proper. "Reports have shown that Trim31-deficient mice lost the ability to inhibit the inflammatory response in colonitis; however, Trim31 was determined to be a positive promoter that could exacerbate cardiomyopathy triggered by inflammation-associated signaling." (PMID 35217669, 2022).
Cerebral ischemia (1 paper, 2022). Restriction of arterial blood supply to the brain associated with insufficient oxygenation to support the metabolic requirements of the tissue. "TRIM31 deficiency alleviated mitochondrial injury induced by cerebral ischemia by upregulating the level of TIGAR protein." (PMID 36437984, 2022). "TRIM31 deficiency alleviates mitochondrial damage induced by cerebral ischemia by upregulating TIGAR protein level." (PMID 36437984, 2022).
cervical cancer (1 paper, 2025). A primary or metastatic malignant neoplasm involving the cervix. "Wnt/β-catenin pathway activity was examined in cervical cancer cells with aberrant expression of TRIM31." (PMID 40919166, 2025). "The effects of TRIM31 on the proliferation of cervical cancer cells were investigated, and TRIM31 significantly increased proliferation in vitro." (PMID 40919166, 2025). "In cervical cancer cells, TRIM31 is highly expressed in cervical cancer cells and carcinoma tissues and promotes the proliferation of cervical cancer cells." (PMID 40919166, 2025). "The results of the RNA sequence in Snai2-overexpressing cervical cancer cells implied a strong correlation between Snai2 and TRIM31 with ubiquitin ligase activity." (PMID 40919166, 2025). "TRIM31 was detected in the C-33 A, SiHa and HeLa cervical cancer cell lines and was highly expressed in SiHa and HeLa cells." (PMID 40919166, 2025). "In brief, TRIM31 promoted the proliferation of cervical cancer cells, whereas defects in the expression of TRIM31 impaired cervical cancer cell proliferation." (PMID 40919166, 2025). "This study is the first to confirm that TRIM31 is upregulated in cervical cancer and promotes the proliferation of cervical cancer cells." (PMID 40919166, 2025). "Currently, the role and potential molecular mechanism of TRIM31 in cervical cancer are still unknown." (PMID 40919166, 2025). "In summary, similar with its role in other tumors, TRIM31 may promote the proliferation of cervical cancer cells through the classical Wnt pathway." (PMID 40919166, 2025). "Despite our intention to analyze the correlation between TRIM31 and the survival of cervical cancer patients using online databases, regrettably, no significant positive results were obtained." (PMID 40919166, 2025).
Crohn disease (1 paper, 2016). A gastrointestinal disorder characterized by chronic inflammation involving all layers of the intestinal wall, noncaseating granulomas affecting the intestinal wall and regional lymph nodes, and transmural fibrosis. "To explore the functional roles of TRIM31 in intestine, we next examined TRIM31 expression in samples from patients with Crohn's disease or controls." (PMID 27216961, 2016). "Remarkably, TRIM31 expression decreased by ∼45% in Crohn's disease patients compared with normal ileum tissues." (PMID 27216961, 2016). "TRIM31 was enriched in the mitochondria and its aberrant expression with very low intensity was shown in samples from Crohn's disease patients, leading us to focus our investigation to TRIM31 and its role in autophagy." (PMID 27216961, 2016). "Additionally, in contrast to normal samples, the level of TRIM31 mRNA in Crohn's disease patients decreased by 85%, suggesting that TRIM31 is downregulated in Crohn's disease due to a defect in transcription." (PMID 27216961, 2016).
dyslipidemia (1 paper, 2022). "Collectively, our data revealed the positive effects of Trim31 on mitigation of steatohepatitis and associated metabolic syndrome in mice." (PMID 35217669, 2022).
fatty liver (1 paper, 2022). "Collectively, the protective effects of Trim31 on the regulation of hepatic steatosis and inflammation can be primarily attributed to the Trim31-Rhbdf2 interaction and the RING-finger domain of Trim31." (PMID 35217669, 2022). "To determine whether Trim31 is involved in hepatic steatosis and metabolism, we first investigated its expression levels in liver tissues isolated from both dietary and obese mice models with steatohepatitis." (PMID 35217669, 2022). "In our present work, we found that Trim31 has the ability to suppress liver steatosis and improve insulin signaling and hepatic inflammation by promoting Rhbdf2 degradation via K48-linked ubiquitination, further restraining Rhbdf2-MAP3K7 activity and downstream events." (PMID 35217669, 2022). "Once the interaction between Rhbdf2 and Trim31 was blocked, the protective function of Trim31 on HFD-induced liver steatosis was strongly inhibited." (PMID 35217669, 2022). "In addition, the additional multiple linear regression and Pearson multiple correlation analyses further confirmed the negative correlation of liver Trim31 expression with fatty liver severity." (PMID 35217669, 2022).
fungal infection (1 paper, 2021). "Trim31+/+ mice reconstituted with Trim31−/− BM displayed a phenotype similar to that of mice with total Trim31 deficiency after fungal infection, indicating the radiosensitive hematopoietic cells were involved in the anti-fungal immune response." (PMID 34362877, 2021). "Overall, our study first reported that SYK was modified through K27-linked polyubiquitination by TRIM31 upon fungal infection, and also uncovered its significance in positively regulating the activation of SYK-associated signaling cascades and the resultant anti-fungal immunity." (PMID 34362877, 2021). "Consistently, Trim31-deficient mice were more sensitive to fungal infection than Trim31+/+ mice." (PMID 34362877, 2021). "The result showed that Trim31−/− mice were more sensitive to fungal infection than Trim31+/+ mice." (PMID 34362877, 2021).
gastric adenocarcinoma (1 paper, 2022). "Moreover, TRIM31 can be recognized as a growth suppressor at the early stage of gastric adenocarcinoma." (PMID 36620540, 2022).
glioblastoma (1 paper, 2023). The most malignant astrocytic tumor (WHO grade IV). "Some studies have demonstrated that TRIM31 is involved in tumor growth and metastasis in nasopharyngeal carcinoma, glioblastoma, pancreatic and colorectal cancer." (PMID 37973999, 2023). "Several studies have demonstrated that TRIM31 was elevated in several malignant carcinomas, such as nasopharyngeal neoplasms, glioblastomas, and colorectal cancers." (PMID 37973999, 2023).
high blood pressure (1 paper, 2022). "Besides, traits association analysis showed that 3 SNPs (rs62394289 in the SLC17A3 gene, rs9378220 in TRIM31, rs112733823 in LINC00243) were associated with other potential risk factors of stroke (high blood pressure and Rheumatoid arthritis) and therefore, were also excluded." (PMID 36741373, 2022).
Impaired glucose tolerance (1 paper, 2018). An abnormal resistance to glucose, i.e., a reduction in the ability to maintain glucose levels in the blood stream within normal limits following oral or intravenous administration of glucose. "We found that TRIM31−/− mice had impaired glucose tolerance and decreased insulin sensitivity, accompanied by moderate inflammation activation." (PMID 29497383, 2018).
lentivirus infection (1 paper, 2024). Virus diseases caused by the Lentivirus genus. "Western blot was utilized to test the efficacy of lentivirus infection, and it was discovered that the decrease in TRIM31 expression in TRIM31-sh3 AGS cells was the most significant." (PMID 38978046, 2024).
leukaemia (1 paper, 2025). "cg04016431 is located in the TRIM31 gene body, which has been implicated in cancers, including leukaemia." (PMID 40490854, 2025).
liver disease (1 paper, 2024). "Among these, suppressor of cytokine signaling 2 (SOCS2) and TRIM31 were analyzed separately due to their likely involvement in persistent viral infection and liver disease development." (PMID 39211324, 2024).
lung adenocarcinoma (1 paper, 2022). A carcinoma that arises from the lung and is characterized by the presence of malignant glandular epithelial cells. "For example, other cancer types such as Lung Adenocarcinoma (LUAD) or Liver Hepatocellular Carcinoma (LIHC) may also exhibit increased susceptibility to COVID-19 infection via similar mechanisms governed by TMPRSS2, TMPRSS4, and TRIM31, however this remains to be further investigated." (PMID 35970857, 2022).
lymph node metastasis (1 paper, 2023). "TRIM31 upregulation was positively associated with the TNM stage (P = 0.021), depth of invasion (P = 0.003), and lymph node metastasis (P = 0.041)." (PMID 37973999, 2023).
cancer (30 papers, 2016 to 2026). A tumor composed of atypical neoplastic, often pleomorphic cells that invade other tissues. "Other dysregulated signaling pathways are responsible for TRIM31 functions including NF-κB and Akt pathways, which are tightly associated with cancer cell proliferation and invasion." (PMID 37973999, 2023). "High TRIM31 expression associates with poor prognosis and drug resistance in various cancers including colorectal, pancreatic, and liver cancers." (PMID 33311639, 2020). "The strict regulation of the TRIM31 protein level may be linked to its seemingly contradictory behaviors in the cancer process." (PMID 36620540, 2022). "In addition, TRIM31 has been proven to be associated with radiosensitivity and chemosensitivity in cancers." (PMID 32232394, 2020). "Within this context, a distinct subtype of C4 TRIM31+ TCs exhibiting immunoregulatory features was characterized, suggesting their involvement in shaping the cancer immunity landscape of CRC." (PMID 42292420, 2026). "Here we identified that the E3 ligase TRIM31, a member of the TRIM (Tripartite Motif) family proteins, is highly expressed during colorectal inflammation-cancer transformation and is associated with poor prognosis in CRC patients." (PMID 40819060, 2025). "TRIM31, an E3 ubiquitin ligase of the TRIM family, is associated with cancer, immune diseases, and metabolic dysfunction." (PMID 39211324, 2024). "The role of TRIM31 in regulation of tumorigenesis was related to various cell signaling pathways in different cancers." (PMID 38978046, 2024). "It was found that the sensitivity of cancer therapy was influenced by the expression level of TRIM31." (PMID 38978046, 2024). "In this study, we defined TRIM31 as a cancer-promoting mediator that regulates the Wnt/β-catenin pathway." (PMID 37973999, 2023). "These seemingly contradictory studies suggest that TRIM31 plays various roles in different cancer types." (PMID 37973999, 2023). "Recently, increasing evidence has shown that TRIM31 plays an important tumor suppressor role in the occurrence and development of various cancers." (PMID 36620540, 2022). "Activation of the NF-κB pathway is also positively correlated with TRIM52, TRIM14, and TRIM31 and promotes cancer development in cancers." (PMID 36261847, 2022). "TRIM31 is a critical factor that is able to perform multiple functions in cancer, and the complex function of TRIM31 makes it difficult to identify TRIM31 as an oncogene or tumor suppressor." (PMID 36620540, 2022). "Recent studies on TRIM31 strongly advocate for the critical role of TRIM31 in cancer, immunity and inflammation." (PMID 36620540, 2022). "The expression of TRIM31 in diverse cancer cells is different, and its expression is tightly controlled by various factors." (PMID 36620540, 2022). "In ovarian cancer, microRNA-551b downregulates TRIM31 expression by targeting its 3’ UTR to promote cancer progression." (PMID 36620540, 2022). "Several reports have revealed that there is a positive correlation between the expression of TRIM31 and cancer prognosis in specific cancer types." (PMID 36620540, 2022).